ALB (albumin)
Diseases named in the same sentence as ALB in open-access papers (continued):
Sharing a sentence is not in itself a finding about the gene and the disease.
COVID-19 (continued). "Our findings suggest that albuminuria is only a short-term complication of mild COVID-19, as our multivariable repeated measures showed minor fluctuations of serum albumin at 3- and 6-month post-infection that were statistically not significant." (PMID 35877031, 2023). "In another study, in non-survivors, the serum albumin values were below the normal reference range and were significantly lower in non-survivors than in survivors, suggesting that a decline in liver synthesis function may be a key factor for COVID-19-associated mortality." (PMID 37810906, 2023). "Compared with the moderate COVID-19 group, patients with mild COVID-19 were younger, had a shorter dialysis vintage, a lower prevalence of DM, CAD, or TB, lower IL-6 and PCT levels, and higher post-infection albumin level (p < .05)." (PMID 37501590, 2023). "Higher GGT levels were associated with lower albumin and higher CRP, ALT, and ALP levels in the 82 COVID-19 patients who did not have chronic liver disease or an alcohol history." (PMID 36747045, 2023). "Hypoalbuminemia is not a result of reduced synthesis in severe COVID-19, but a result of albumin consumption." (PMID 36676691, 2022). "In conclusion, the increase in CRP, PCT, ESR, ferritin, troponin, D-dimer, LDH, and neutrophil count and the decrease in albumin, PLT, and lymphocyte count are significant in the severe patient group, and it is thought that they can help in determining the severity of COVID-19." (PMID 35950826, 2022). "In COVID-19 patients with comorbid conditions, statistically significant changes were obtained for sodium, potassium, CRP, ferritin, creatinine, total protein, and albumin." (PMID 35165642, 2022). "However, in COVID-19 ARDS, we see a lower overall serum albumin level, and yet pulmonary vascular dilation still occurs." (PMID 35456942, 2022). "In addition, albumin-based scores such as the CRP-to-albumin ratio (CAR) and PNI were also good predictors of COVID-19 disease severity." (PMID 36296963, 2022). "The binding of this higher molecular mass albumin was not a specific unique feature of plasma from patients who had recovered from COVID-19 ARDS but was also found to occur in seronegative and seropositive healthcare worker (HCW) samples." (PMID 35456942, 2022). "After the COVID-19 outbreak, the characteristics of KD patients showed a younger trend of age, shorter hospitalization days and higher levels of albumin, but the incidence of CALs did not change significantly." (PMID 35656374, 2022). "When compared to controls, COVID-19 patients had significantly lower concentrations of ADAMTS13 and albumin (ALB) but higher M30, M65, α1-acid glycoprotein (AGP), α1-antitrypsin (AAT), ceruloplasmin (CP), haptoglobin (HP), and high-sensitivity C-reactive protein (hs-CRP)." (PMID 36514048, 2022). "In the case of albumin, it is more susceptible to non-enzymatic glycation reactions and regulates the expression of ACE2, which is the target receptor of COVID-19." (PMID 36006242, 2022). "In addition, studies have validated the predictive value of other indicators, such as D-dimer and albumin/creatinine ratio, for AKI in hospitalized COVID-19 patients." (PMID 36505004, 2022). "Moreover, we identified seven possible pharmacological targets of vitamin D against COVID-19/HCC, including HMOX1, MB, TLR4, ALB, TTR, ACTA1 and RBP4." (PMID 36275701, 2022). "This study indicated some demographic characteristics of COVID-19 infected hemodialysis patients including age, gender, ARDS status, BMI, co-morbidities, and laboratory signs (e.g., low albumin levels and increased LDH) that were attributed to the disease outcome." (PMID 36511252, 2022). "Biochemical indicators: The albumin concentration was significantly reduced in COVID-19 patients with AKI (29.6 g/L) compared with those without AKI (33.9 g/L)." (PMID 35656097, 2022).
COVID-19 (continued). "A meta-analysis performed through 3 April 2020, included 11 articles with 910 patients, comparing albumin levels in severely and non-severely ill COVID-19 patients." (PMID 35160039, 2022). "A recent report of dialysis patients with COVID-19 in Japan revealed that older age (> 70 years), higher BMI, higher CRP level, and lower serum albumin levels, were aggravating factors of mortality, and that the use of remdesivir was predictive of improved mortality." (PMID 36101873, 2022). "According to our research, lower albumin levels on admission can predict COVID-19 outcomes irrespective of most comorbidities and better than NLR." (PMID 35956107, 2022). "DPP4, albumin, and LDH were significantly upregulated in the airways of patients post-COVID-19 compared with HCs, validating the observations made by Olink and confirming the presence of ongoing damage within the respiratory tracts of patients previously hospitalized for COVID-19." (PMID 35151371, 2022). "Presently, we witnessed an increased level of neutrophils, procalcitonin, WBC, EST, and AST and a decreased level of albumin in COVID-MRSA pneumonia patients, whereas LDH, D-dimer, ferritin, troponin-I, CK, and CRP were increased in both COVID-MRSA as well as in COVID-19 patients." (PMID 35997388, 2022). "Urea and albumin/creatinine ratio were higher in the COVID-19-positive group than in the COVID-19-negative group." (PMID 35632392, 2022). "Biomarkers such as white blood cell, neutrophil, lymphocyte, eosinophil, platelet count, total bilirubin, albumin, and creatinine showed values significantly lower in COVID-19-positive compared to negative patients." (PMID 33946171, 2021). "LDH, CRP and ALB are useful prognostic marker for predicting nucleic acid turn negative within 14 days in symptomatic patients with COVID-19." (PMID 33663273, 2021). "In line with lack of albumin normalization in COVID-19 patients with no improvement, it would be worthwhile to see how the Covichem score value evolves during the hospitalization, and its capacity to predict patient improvement." (PMID 33956870, 2021). "COVID-19 survivors exhibited significant higher values of ALT, AST, GGT (P < 0.001), and ALP (P = 0.001) but with statistically significant reduction of serum albumin (P < 0.001)." (PMID 34777873, 2021). "Unfortunately, there is currently a lack of robust data on albumin infusion's therapeutic value and even more scarce data in patients with COVID-19." (PMID 34367693, 2021). "Furthermore, the severe patients had decreased levels of albumin but increased levels of alanine aminotransferase (ALT), procalcitonin, lactate dehydrogenase compared to the patients with the moderate and mild COVID-19." (PMID 33763078, 2021). "Unfortunately, the correlation between COVID-19 severity and low albumin levels were not analyzed in this study due to its small sample size and limited data collection period, which are the limitations of this study." (PMID 33585030, 2021). "In this single-center study of 160 consecutive critically ill COVID-19 patients with moderate to severe ARDS demanding high oxygen flow, serum albumin, IL-6, and D-dimer at admission to ICU, accompanied by a chest CT severity score, were marked as independent predictors of mortality." (PMID 33968298, 2021).
COVID-19 (continued). "Also, cancer patients with severe/critical COVID-19 tended to be male and present with low SPO2 and albumin, and high hs-CRP, lactate dehydrogenase and blood urea nitrogen on admission compared to those with mild COVID-19." (PMID 33995633, 2021). "The COVID-19 versus CAP classifiers with the highest performance also involved PCT, MCHC, uric acid, albumin, neutrophil count, monocyte count, basophil count, RBC count, and WBC count, proposing the importance of these CLIs in differentiating COVID-19 from CAP." (PMID 33534722, 2021). "Regarding the role of prealbumin in re-positive patients, it was an acute negative time reactive protein similar to albumin, of which the level was significantly lower in COVID-19 patients with a poor prognosis than in those with a good prognosis." (PMID 34026776, 2021). "It revealed that LDH, ALB, TP and CRP were correlated with whether nucleic acid turned negative within 14 days, AST, LDH, ALB, CRP and PCT were correlated with severity of COVID-19, and ALB and CRP was correlated with hospital stay > 31days or not (P < 0.05)." (PMID 33663273, 2021). "Other features, including serum CO2, hemoglobin and hematocrit, albumin, and edema, were selected by the models but did not have a known connection with COVID-19." (PMID 34633425, 2021). "The elevated levels of albumin (47.6%), globulin (42%), ALT (33.5%), AST (30.7%), D-dimmer (47.6%), and creatinine (25.5%) were observed during laboratory investigation of patients with COVID-19." (PMID 34828513, 2021). "A secondary aim of this study is to assess for any significant differences in serum biomarkers of liver injury (alanine transaminase [ALT], aspartate transaminase [AST], total bilirubin, and albumin) in patients with severe versus non-severe COVID-19." (PMID 32864250, 2020). "Both survivors and nonsurvivors COVID-19 patients presented abnormal values for haemoglobin, D-dimer, albumin and all inflammatory factors." (PMID 33141836, 2020). "Comparison of routine blood tests across the two timepoints demonstrates an acute, significant shift in the circulating levels of albumin, C-reactive protein, alanine amino-transferase (ALT), sodium, hemoglobin, lymphocyte, and platelet counts at COVID-19 diagnosis secondary to the acute illness." (PMID 32650523, 2020). "Albumin is fortunately not normally found at any significant levels in saliva and S2b should be evident in COVID-19-positive gargle/saliva samples." (PMID 32987950, 2020). "The mean, standard deviation and concentration range of albumin from the COVID-19 patients and unexposed negative controls were 9.6 ± 8.1 μg/ml (1.3 μg/ml – 32.6 μg/ml) and 9.3 ± 9.4 μg/ml (1.2 μg/ml – 45.8 μg/ml), respectively." (PMID 33033173, 2020). "In non-severe COVID-19 patients, total protein, albumin, and sodium levels were not significantly different across different age groups (< 50, 50–60, 60–70, and ≥ 70 years)." (PMID 33065551, 2020). "Coincidentally, all of these studies did not elucidate the role of albumin in the prediction on disease severity or prognosis of COVID-19." (PMID 33110593, 2020). "Compared with the non-infected hemodialysis patients, patients with COVID-19 had a significantly shorter dialysis age, lower level of plasma albumin, the higher level of blood creatinine, potassium, and parathyroid hormone (all p < .05)." (PMID 32924707, 2020). "In addition, decreased hemoglobin, lymphocyte side scatter (LY-SSC), and albumin, as well as increased leukocyte and monocyte side scatter (MO-SSC), were associated with a greater severity, regardless of COVID-19 status." (PMID 40506946, 2025).
COVID-19 (continued). "These linear peptides were coupled to bovine serum albumin (BSA), and blot hybridization was used to investigate antigen–antibody reactions among the peptides, commercial anti-S protein polyclonal antibodies, and sera derived from vaccinated individuals and those with confirmed COVID-19." (PMID 41170287, 2025). "In our results, and from our experiences, the reason for the differences in serum albumin between the COVID-19 and H1N1 groups lies in the fact that the patient with Influenza type A (H1N1) ARDS required mechanical ventilation earlier in the onset of the disease than the patient with COVID-19." (PMID 40017475, 2025). "Recently, blood SPL concentrations have been correlated with COVID-19 severity in humans and animal models: blood concentrations of S1P, total HDL, ApoM, and the ratio of ApoM- versus albumin-bound S1P may be some of the most reliable predictors of COVID-19 morbidity and mortality." (PMID 40386785, 2025). "Interestingly, the ALB levels in patients with COVID-19 and myocarditis were virtually identical, with no statistical significance between them." (PMID 38303719, 2024). "In addition, to analyze the interplay between coagulation and inflammation and COVID-19 severity, we analyzed levels of D-dimer, albumin, and hs-CRP in patients with and without ARDS." (PMID 39456513, 2024). "Albumin infusion combined with conventional anti-aggregators may be the optimal anticoagulant therapy for critically ill patients with or without COVID-19." (PMID 39612427, 2024). "A similar pattern of expression was observed in our cohort, with elevated levels of SAA (p < 0.0001*), CRP (p < 0.0001*), and LBP (p < 0.0001*) alongside a decrease in ALB (p < 0.0001*) in all unhealthy individuals presenting ill at the hospital, regardless of COVID-19 status." (PMID 38879593, 2024). "In conclusion, the lactate/albumin ratio at ICU admission, easily obtained from routine laboratory tests, performs better than lactate alone, and it could serve as a reliable indicator for the prognosis of critically ill COVID-19 patients." (PMID 39685564, 2024). "Higher levels of Albumin was found to be acceptable indicator of maintenance on non-invasive ventilation while higher levels of Sodium and PCT were found to be fair predictor of requirement of invasive ventilation in intensive care of severely ill COVID-19 patients." (PMID 37969877, 2023). "Common laboratory abnormalities in COVID-19 patients include leukopenia, thrombocytopenia, increased levels of inflammatory markers such as C-reactive protein (CRP) and cardiac biomarkers, decreased albumin levels, and deviated serum markers of renal and liver function." (PMID 36986138, 2023). "Although the fibrosis-4 (FIB-4) index, aspartate aminotransferase-to-platelet ratio index (APRI), and albumin-bilirubin grade (ALBI) score can predict mortality in CLD, their correlation with the clinical outcomes of CLD patients with coronavirus disease 2019 (COVID-19) is unclear." (PMID 38077441, 2023). "In addition, it was shown that male gender, severe COVID-19, and lactate dehydrogenase were significant positive predictors, while albumin level was a significant negative predictor of Brixia score." (PMID 37371019, 2023). "We confirmed this CRP data, and, since we focused on the blood biochemical parameters, we did show that TnT, FBG, glycemia, CPR, LDH, albumin, D-dimer, MGB, and ferritin for both men and women might represent useful indicators of severe morbidity and mortality for Omicron COVID-19." (PMID 37110348, 2023). "Although there have been no previous studies on the association between ALB and COPD progression, a meta-analysis including 6 studies demonstrated that severe COVID-19 patients had a higher prevalence of COPD and were significantly associated with decreased ALB levels." (PMID 37033218, 2023).
COVID-19 (continued). "This study identified significant predictors for COVID-19 severity, including older age, presence of chronic disease, high WBC count, high neutrophil count, low lymphocyte count, low hemoglobin, high D-dimer, high CRP, high ferritin, high troponin T, high creatinine, low albumin, and high ALP." (PMID 38130539, 2023). "In addition, we did not have albumin data to evaluate the disease prognosis o severity; however, this is the first study that assessed the variant rs16969968 (CHRNA5) in severe COVID-19." (PMID 37372959, 2023). "We estimated that albumin may be a better predictor of the COVID-19-severity course compared to NLR, irrespective of comorbidities (p < 0.001)." (PMID 35956107, 2022). "Furthermore, and unlike LDH, serum albumin concentration as a negative APP representative of inflammation was lower in the non-survival group compared to the COVID-19 survivals." (PMID 36614820, 2022). "The severity of COVID-19 disease progression among SARS-CoV-2-infected individuals was significantly correlated with higher serum levels of ALT, AST, and total bilirubin and lower serum levels of albumin, and 62% of COVID-19 ICU patients had elevated levels of AST." (PMID 36189356, 2022). "However, regression analysis showed that only ALB, NLR, CD4/CD8 ratio, and eosinophil count were risk predictors for the viral shedding duration in patients with non-severe COVID-19." (PMID 36620263, 2022). "However, in severe COVID-19 patients the strongest positive correlations were found only between plasma levels of ACT and SAA, hs-CRP and AAT, and between CP and AAT, and negative correlations between HP and ACT as well as between HP and ALB." (PMID 36514048, 2022). "Thus, a decrease in albumin in COVID-19 patients, probably due to a not adequate nutrition or to an increased catabolism, caused a reduction in the weak acids with an alkalinizing effect." (PMID 35456186, 2022). "In addition, COVID-19 patients with PE had higher NT-pro BNP (MD 94.24 pg/mL; 95% CI 45.21 – 143.27; P = .0002), hs Troponin I (MD 5.00 ng/L; 95% CI 1.01 – 8.99; P = .01), but lower albumin (MD -3.58 g/L; 95% CI -5.18 to -1.98; P < .0001)." (PMID 36397410, 2022). "Our results indicated that COVID-19 patients with PE always experienced more ICU admission, longer time from illness onset to admission, more mechanical ventilation and IMV, higher baseline and peak serum D-dimer, higher NT-pro BNP and hs Troponin I, but lower albumin." (PMID 36397410, 2022). "To date, some articles have demonstrated that Tc-99m macroaggregated albumin (Tc-99m MAA) Q-SPECT/CT is a safe procedure without the increased risk of spreading contagious aerosols and enables to diagnose PE in patients with COVID-19, if contrast enhanced CT is contraindicated." (PMID 35763163, 2022). "A low albumin level could increase the ROS level in COVID-19 patients, and retrospective studies have shown that hypoalbuminemia indicates the COVID-19 severity independent of age and co-morbidity." (PMID 36290783, 2022). "Further, we identified seven overlapping genes of vitamin D against HCC and COVID-19 using the network pharmacology approach, and the anti-COVID-19/HCC effects of vitamin D may be modulated by these molecules or genes, including HMOX1, MB, TLR4, ALB, TTR, ACTA1 and RBP4." (PMID 36275701, 2022). "We also do not have an obese animal model of COVID-19 to test the hypothesis that unbound fatty acids worsen COVID-19 in these models, nor do we provide proof of albumin having a therapeutic role in these." (PMID 35502320, 2022). "For blood test results, albumin and lymphocyte counts were lower in severe patients than non-severe patients, while the prothrombin time (PT) was longer in severe COVID-19 patients than non-severe COVID-19 patients (all Kruskal Wallis rank p values < 0.001)." (PMID 35521216, 2022).